AMH (anti-Mullerian hormone)
Diseases named in the same sentence as AMH in open-access papers (continued):
Sharing a sentence is not in itself a finding about the gene and the disease.
premature ovarian failure (continued). "Turner’s syndrome patients with X monosomy or with the absence of spontaneous pubertal development and premature ovarian failure had already very low levels of AMH before 25 years (AMH < 2–7 pmol/L)." (PMID 38116311, 2023). "AMH was shown to be effective as a predictor of absent puberty, as AMH ≤2 SD for age predicted failure to enter puberty in young girls with TS and imminent primary ovarian insufficiency in adolescent and adult patients with TS." (PMID 29699389, 2018). "The charateristics of premature ovarian failure is an increased FSH and decreased AMH level." (PMID 28208728, 2017). "The term primary ovarian insufficiency (POI) includes both POF and occult indicators of ovarian function, such as increased levels of follicle stimulating hormone (FSH) and decreased levels of anti-Müllerian hormone (AMH)." (PMID 25147555, 2014).
amenorrhea (29 papers, 2015 to 2026). The absence of menses in a woman who has achieved reproductive age. "The risk of amenorrhea can be predicted by pretreatment AMH levels, with the risk of persistent amenorrhea higher with a lower pretreatment AMH." (PMID 38003481, 2023). "Increased female age is significantly associated with a reduced risk of oligo/amenorrhea but it is insignificant in AMH adjusted model." (PMID 34177795, 2021). "When adjusted for AMH levels, both short cycles and oligo/amenorrhea were associated with an increased risk of low response [adjusted OR=1.3 (1.02, 1.75), 1.3 (0.93, 1.86), respectively]." (PMID 34177795, 2021). "In our previous study, both estrogen receptor-positive and -negative breast cancer patients were included for analyses, and tamoxifen use was associated with post-chemotherapy serum AMH level as well as amenorrhea." (PMID 32656076, 2020). "Women with greater AMH levels had lower ovarian volume per follicle and this was associated with an increased risk of oligo/amenorrhea." (PMID 31616381, 2019). "Thirty-two years old or older women, serum AMH < 3.32 ng/mL or AFC <13 offer a higher risk of amenorrhea or oligomenorrhea after CTX with cyclophosphamide." (PMID 26667243, 2015). "In February 2023, the serum levels of anti-Mullerian hormone (AMH) of this patient was 1.02 pmol/L (0.14 ng/ml), so we speculate that decreased ovarian reserve may be the main cause of amenorrhea in this patient." (PMID 38166803, 2024). "Lower baseline serum AMH levels, and hence a lower ovarian reserve in women with gBRCApv may have also contributed to the predisposition to amenorrhea risk." (PMID 37698031, 2023). "Additionally, AMH has the advantage of being able to distinguish oligo/amenorrhea caused by PCOS versus premature ovarian failure or hypergonadotropic hypogonadism." (PMID 36900051, 2023). "Moreover, our results showed that AMH levels were associated with menstrual cycle status, which was consistent with previous study showing that AMH had strong diagnostic ability for amenorrhea by receiver operating characteristic (ROC) curve analysis." (PMID 35236324, 2022). "To investigate whether elevated AMH levels were associated with oligo/amenorrhea, we stratified AMH levels by 0-25th, 25-50th, 50-75th, 75-100th percentile." (PMID 34177795, 2021). "Finally, longitudinal analyses confirmed a beneficial effect of high baseline AMH levels on the risk of amenorrhea during the follow‐up (ROR = 0.91 [95% CI = 0.86–0.97], p = 0.002) for differential time trends (per month) in the event rate for high versus low (> vs. ≤2.0 ng/mL) AMH groups." (PMID 37698031, 2023). "Nonetheless, feature-level comparisons remain meaningful: across studies, older age, lower AMH, and higher FSH consistently predicted increased risk of amenorrhea, supporting the biological plausibility of our findings." (PMID 41301127, 2025). "In our study, we examined 53 potential features and identified factors such as BRCA mutations, a higher number of AC+CMF cycles, older age, lower E2, lower AMH, and higher FSH as contributors to increased amenorrhea risk." (PMID 41301127, 2025). "Clinically, the disease usually manifests amenorrhea, hypergonadotropism, hypoestrogenism, and low levels of the anti-Mullerian hormone (AMH) before the age of 40 years." (PMID 37957472, 2024). "The discriminative and predictive abilities of AMH in the prediction of amenorrhea at different time points in all patients were assessed." (PMID 37698031, 2023). "We found that age at the onset of treatment as previously known, pre‐ and post‐treatment AMH levels, and as a novel finding, gBRCApv status can be predictors of amenorrhea at 12–18 months." (PMID 37698031, 2023). "Based on the ROC curve analysis with baseline AMH as predictor and 12‐month amenorrhea, optimal cutoff of ~1.7 ng/mL was suggested by Youden index and correct classification, and ~2.0 ng/mL was suggested by the two other measures." (PMID 37698031, 2023).
amenorrhea (continued). "An undetectable AMH immediately post‐chemotherapy was predictive of amenorrhea with <18 month follow‐up." (PMID 37698031, 2023). "The clinical diagnostic criteria of POF is amenorrhea together with elevated gonadotropin levels (follicle-stimulating hormone [FSH] > 20 IU/L), low estradiol (E2) levels (< 20 pg/mL), and low anti-Müllerian hormone (AMH) levels –< 0.5 ng/mL (< 1 ng/mL)." (PMID 36289509, 2022). "PCOS women with amenorrhea demonstrated significantly greater serum AMH level than oligoovulatory women (8.95 ng/mL, n = 64 vs. 6.80 ng/mL, n = 338, P = 0.002)." (PMID 35236324, 2022). "In women with PCOS, compared to women with a normal menstrual cycle, women with short cycles and women with oligo/amenorrhea showed higher antral follicle count and higher serum AMH levels." (PMID 34177795, 2021). "In women with PCOS, compared to women with a cycle length of 26-35 days, women with short cycles and women with oligo/amenorrhea showed higher antral follicle count and higher serum AMH levels." (PMID 34177795, 2021). "Our study shows that women with low AMH values are more likely to have very few oocytes collected if they show oligo/amenorrhea compared to those with the normal menstrual cycle." (PMID 34177795, 2021). "Serum AMH levels, antral follicle count, and oocyte retrieval numbers were significantly lower in women with short cycles and higher in women with oligo/amenorrhea than those with a normal menstrual cycle." (PMID 34177795, 2021). "The odds of oligo/amenorrhea were increased by 6.7-fold (95% CI 2.5–19.9) in those with an AMH per antral follicle of >2 pmol/L when compared with those with an AMH per antral follicle of <1 pmol/L (P < 0.0001)." (PMID 31616381, 2019). "Oligo/amenorrhea was present in one third of women; women with oligo/amenorrhea had higher BMI (25.0 vs. 23.3 kg/m2), AMH (65.6 vs. 34.8 pmol/L), AFC (38 vs. 29), and FAI (3.0 vs. 2.1%)." (PMID 31616381, 2019). "Median serum AMH was significantly higher in women with oligo/amenorrhea when compared to women with regular menstrual cycles (65.6 vs. 34.8 pmol/L; P < 0.0001)." (PMID 31616381, 2019). "The odds of oligo/amenorrhea were increased 28.5-fold (95% CI 3.6–227.3) in women with AMH >60 pmol/l, when compared to those with AMH < 15 pmol/L." (PMID 31616381, 2019). "≥32-years-old women, AMH <3.32 ng/mL and AFC <13 follicles determined significantly higher risk of amenorrhea or oligomenorrhea after CTX with cyclophosphamide." (PMID 26667243, 2015). "AMH cutoff to predict amenorrhea was 1.87 ng/mL (sensitivity 82 %, specificity 83 %, AUC 0.84) and AFC cutoff was 9 follicles (sensitivity 71 %, specificity 78 %, AUC 0.73)." (PMID 26667243, 2015). "ovarian reserve marker (ORM) with power to predict amenorrhea or oligomenorrhea in women after CTX were AMH <3.32 ng/mL (sensitivity of 85 %, specificity of 75 % and AUC 0.87), AFC <13 follicles (sensitivity 81 %, specificity 62 %, AUC 0.81)." (PMID 26667243, 2015). "Furthermore, it was reported that AMH concentrations were lower in women who experienced primary amenorrhea than in those with secondary amenorrhea." (PMID 39391877, 2024). "Pregnancy can occur even in the presence of low post-chemotherapy AMH levels, below 1 ng/mL, documenting that AMH levels do not predict short-term fertility, unless associated with amenorrhea." (PMID 37766870, 2023). "In multivariable‐adjusted logistic regression, age (p = 0.03) and AMH (p = 0.03) at 12 months, and gBRCApv status (p = 0.03) at 18 months were significant predictors of amenorrhea (areas under the ROC curve of 0.77 and 0.76, for 12 and 18 months, respectively) among 102 evaluable subjects." (PMID 37698031, 2023). "All three studies looked at the value of AMH in prediction of amenorrhea risk, but none with the incorporation of gBRCApv status as a predictor." (PMID 37698031, 2023). "Serum AMH may also be a marker of ovulatory dysfunction, including both oligomenorrhea and amenorrhea." (PMID 36900051, 2023).
amenorrhea (continued). "One study of 148 women demonstrated that substituting AMH with a cut-off of 3.19 ng/mL for oligo/amenorrhea in the Rotterdam criteria could accurately diagnose PCOS, with an AUC 0.938, sensitivity 81%, and specificity 100%." (PMID 36900051, 2023). "Subsequently, the patient developed amenorrhea, and her AMH on day 47 of amenorrhea was 35.2 ng/mL." (PMID 33828986, 2021). "To summarize, our study shows that elevated AMH levels are significantly associated with increased risk of oligo/amenorrhea in women with and without PCOS." (PMID 34177795, 2021). "AMH levels are significantly associated with increased risk of oligo/amenorrhea in women with and without PCOS." (PMID 34177795, 2021). "Indeed, women with higher AMH per antral follicle had increased odds of oligo/amenorrhea than those with lower values." (PMID 31616381, 2019). "Furthermore, whilst AMH levels correlated with AFC, serum AMH better predicted the risk of oligo/amenorrhea than AFC." (PMID 31616381, 2019). "In the present study, the risk of oligo/amenorrhea was gradually increased with serum AMH level rather than the risk being defined by a single threshold." (PMID 31616381, 2019). "Low AMH levels were also correlated with longer amenorrhea at V1 (p = 0.014) and V4 (p = 0.035)." (PMID 28877720, 2017). "Thus, given the difficulties of diagnosing PCOS with other criteria, a reliable predictor of oligo/amenorrhea in the form of serum AMH could be helpful diagnostically in this age group." (PMID 36900051, 2023). "Indeed, the serum levels of AMH markedly decreased even after ovarian protection with GnRH agonists in our study and a recent study even though both studies presented beneficial effects for preventing chemotherapy-related amenorrhea." (PMID 32656076, 2020). "Changes in hormone levels (LH, FSH, E2 and Anti-Müllerian hormone (AMH)), antral follicle count (AFC), and amenorrhea were determined before (V1), and 6, 12 and 24 months after the initiation of chemotherapy (V2-V4)." (PMID 28877720, 2017). "The duration of amenorrhea was negatively correlated with the markers of ovarian reserve (AFC and AMH) at nearly all visits, suggesting that regained menstruation is indeed a critical marker of ovarian reserve." (PMID 28877720, 2017). "The ORM age (≥32 years) analyzed together with AMH or AFC increases sensitivity and specificity in predicting amenorrhea or oligomenorrhea." (PMID 26667243, 2015). "Compared with the 0-25th range group of AMH levels, 75-100th percentile groups showed a significantly increased rate of oligo/amenorrhea in women with and without PCOS [adjusted odds ratio (OR) =1.9 (1.04, 3.46), 2.4 (1.70, 3.35)]." (PMID 34177795, 2021). "In women without PCOS and with low AMH levels, the low ovarian response was more common in women with short cycles as well as in women with oligo/amenorrhea [OR=1.5 (1.08, 1.98), 1.7 (1.08, 2.69), adjusted OR=1.2 (0.86, 1.74), 2.2 (1.31, 3.82), respectively]." (PMID 34177795, 2021). "Oligo/amenorrhea is an independent risk factor associated with a low ovarian response in women without PCOS, particularly those with low AMH levels." (PMID 34177795, 2021). "We found oligo/amenorrhea is a risk factor in women without PCOS and with AMH levels in the 0-25th percentile but not in the 25-50th, 50-75th, 75-100th percentile (data not shown for 25-50th, 50-75th, 75-100th percentile)." (PMID 34177795, 2021). "Oligo/amenorrhea is an independent risk factor associated with the low ovarian response in women without PCOS, particularly those with low AMH levels." (PMID 34177795, 2021). "The ORM age (≥32 years) analyzed in series with AMH or AFC decrease the sensitivity in order to increases the specificity, making the result clinically useful with sensitivity and specificity around 80 % to amenorrhea or oligomenorrhea after CTX." (PMID 26667243, 2015).
amenorrhea (continued). "Women with amenorrhea (64%) were significantly lower in the goserelin group compared with the control group (90%, p = 0.006) However, the use of menstruation as a surrogate of the ovarian function instead of the FSH, LH, estradiol, and AMH levels is a study limitation." (PMID 39055889, 2024). "In women without PCOS and with low AMH levels, the low ovarian response was more common in women with short cycles as well as in women with oligo/amenorrhea compared to women with normal cycles [OR=1.5 (1.08, 1.98), 1.7 (1.08, 2.69), adjusted OR=1.2 (0.86, 1.74), 2.2 (1.31, 3.82), respectively]." (PMID 34177795, 2021). "Therefore, it worths attention to the potential causes of oligo/amenorrhea in women undergoing ovarian stimulation and oocyte retrieval, particularly in women without PCOS and with low AMH levels." (PMID 34177795, 2021).
ovarian hyperstimulation syndrome (25 papers, 2011 to 2025). A complication of ovulation induction in infertility treatment. "Serum AMH levels are used in individualized follicle-stimulating hormone dosing protocols and may predict the risk of poor response or ovarian hyperstimulation syndrome but has limited value in predicting ongoing pregnancy." (PMID 32770239, 2020). "Moreover, women with high serum AMH are at increased risk for developing ovarian hyperstimulation syndrome, which can abnormally affect endometrial receptivity, thereby affecting IR and LBR." (PMID 32156287, 2020). "In addition, a high serum concentration of AMH before the start of COH has been shown to be associated with increased risk of developing ovarian hyperstimulation syndrome (OHSS)." (PMID 35761734, 2014). "AMH is an important and very sensitive indicator of ovarian reserve and can be further used to predict ovarian response to hormonal stimulation and assess the risk of ovarian hyperstimulation syndrome as a complication of ovulation induction in women with PCOS." (PMID 40283506, 2025). "A high level of AMH (above 4–5 ng/ml) has been associated with a higher risk of hyperresponse and ovarian hyperstimulation syndrome (OHSS) occurrence." (PMID 35568864, 2022). "Antral follicle counts (AFCs) and AMH concentrations of the patient were at high risk of ovarian hyperstimulation syndrome (OHSS)." (PMID 28931393, 2017). "AMH testing is also useful for predicting POR, cycle cancellations, and the risk of ovarian hyperstimulation syndrome." (PMID 40376141, 2025). "Thus, serum AMH level is a reliable marker to obtain the largest number of oocytes while trying to limit the occurrence of ovarian hyperstimulation syndrome." (PMID 26787450, 2016). "To date, however, there are no studies that demonstrate that weight loss has beneficial effects on serum levels of AMH, but above all, it is not certain that normalization can be a sign of better ovulatory outcome or a lower rate of ovarian hyperstimulation syndrome in the course of ART." (PMID 36235799, 2022). "AFC, AMH, and female age are important parameters to predict response to controlled ovarian stimulation (COS) and identify women who are unresponsive to treatment, at risk of canceling the cycle, and hyper-responsive women at higher risk of developing Ovarian Hyperstimulation Syndrome (OHSS)." (PMID 34786902, 2022). "Conversely, no added advantage has yet been confirmed over FSH as well as AMH, in assessing poor response or ovarian hyperstimulation syndrome (OHSS), number of oocytes retrieved or pregnancy outcomes." (PMID 26977116, 2016). "Patientswith ovarian hyperstimulation syndrome (OHSS)have high serum levels of AMH prior to controlledovarian stimulation (COS)." (PMID 26246873, 2015). "Ovarian stimulation has a known dose dependent response to AMH levels and elevated levels, as present in polycystic ovarian syndrome (PCOS), are associated with increased risk of ovarian hyperstimulation syndrome (OHSS)." (PMID 37020210, 2023). "Evaluation of anti-mullerian hormone (AMH) cut-off levels in as-sisted reproductive technology (ART) as predictive factor for individualization ofstimulation protocols and to avoid ovarian hyperstimulation syndrome (OHSS)." (PMID 26246873, 2015). "Moreover, high AMH levels (> 45 pmol/L) are indicative of polycystic ovary (PCO) and these patients are usually susceptible to ovarian hyperstimulation syndrome (OHSS) following hormonal induction." (PMID 22195987, 2011).
anovulation (22 papers, 2013 to 2026). The absence of ovulation. "Micro-pollutants were linked to decreased levels of Anti-Mullerian Hormone (AMH), anovulation, and irregular menstrual periods." (PMID 41347044, 2025). "The negative effect of high AMH levels on ovarian responsiveness to gonadotrophin may reflect the association between high serum AMH levels and increasing severity of anovulation in PCOS." (PMID 38110998, 2023). "High testosterone along with high AMH concentrations decrease the responsiveness of the granulosa cells to FSH, causing anovulation and leading to PCO." (PMID 36766605, 2023). "Level of AMH has also been studied to have correlation with oligo-/anovulation and the level of AMH were 12 times higher among anovulatory PCOS patients with PCOS compared to ovulatory PCOS patients." (PMID 29426356, 2018). "Conversely, the high AMH of PCOS affects follicular growth by inhibiting the expression of aromatase-dependent LH receptor, which reduces the sensitivity of follicles to FSH, causing anovulation." (PMID 38600539, 2024). "Thus, for some authors, in a population of PCOS women, the AMH/AFC ratio was significantly higher in patients with anovulation than in those with an ovulatory phenotype (phenotype C or asymptomatic ultrasound PCO)." (PMID 33013710, 2020). "Our findings suggest that while AMH is a useful marker for diagnosing PCOS, there may be diminishing returns with very high AMH levels, as they may be associated with more severe forms of the condition, including increased risk of anovulation and metabolic disturbances." (PMID 40150054, 2025). "An LH abundance leads to hyperstimulation of thecal cells and a resulting androgen excess, whereas reduced FSH levels and elevated anti-Mullerian hormone (AMH) levels lead to ovarian arrest and anovulation." (PMID 35265039, 2022). "This common PCOS-AGEs-AMH link highly suggests that AGEs could be one of the intermediary players responsible for the high-AMH production and for the AMHs heightened intracellular action, ultimately leading to PCOS-related anovulation." (PMID 36079834, 2022). "Similarly, AMH levels in amenorrheic and oligomenorrheic PCOS patients were found to be higher than those in eumenorrheic PCOS patients, which possibly indicate a role for AMH in the pathogenesis of anovulation in PCOS women." (PMID 34122349, 2021). "However, while AMH is the product of granulosa cells of small preantral follicles, which are increased in women with polycystic ovaries and have a role in inhibiting FSH action, contributing to anovulation, AMH levels are not elevated in all cases of PCOS." (PMID 40868196, 2025).